FTO (FTO alpha-ketoglutarate dependent dioxygenase)
Diseases named in the same sentence as FTO in open-access papers (continued):
Sharing a sentence is not in itself a finding about the gene and the disease.
intrahepatic cholangiocarcinoma (16 papers, 2020 to 2025). A carcinoma that arises from the intrahepatic bile duct epithelium in any site of the intrahepatic biliary tree. "In another study, fat mass and obesity-associated protein (FTO), an m6A eraser, showed altered expression in intrahepatic cholangiocarcinoma, and low FTO expression predicted poor prognosis." (PMID 36401285, 2022). "Next, low expression of FTO is correlated with microvessel density (MVD) in intrahepatic cholangiocarcinoma (ICC), which is predicted to be associated with poor prognosis." (PMID 35937999, 2022). "The knockdown or overexpression of FTO decreases or increases the sensitivity of intrahepatic cholangiocarcinoma cells to cisplatin, respectively." (PMID 35155557, 2022). "FTO is involved in the inhibition of EMT in intrahepatic cholangiocarcinoma (ICC), and ALKBH5 impairs the migration and invasion of pancreatic cancer." (PMID 34211849, 2021). "The level of FTO was found downregulated in clinical samples of intrahepatic cholangiocarcinoma (ICC) and cells in vitro." (PMID 32194861, 2020). "In contrast, FTO is found to be downregulated in intrahepatic cholangiocarcinoma (ICC)." (PMID 33372610, 2020). "In RCC, FTO promotes angiogenesis by inhibiting von Hippel-Lindau tumor suppressor (VHL) expression, whereas in intrahepatic cholangiocarcinoma (ICC), FTO suppresses angiogenesis by inducing TEA domain transcription factor 2 (TEAD2) expression." (PMID 39098905, 2024). "An association was observed between low FTO expression and high CD34 expression in intrahepatic cholangiocarcinoma (ICC)." (PMID 38053093, 2023). "Nevertheless, a tumor suppressor role of FTO has been described in intrahepatic cholangiocarcinoma (ICC) by controlling different pathways, including EGFR, and by decreasing the stability of the oncogene TEAD2." (PMID 37369946, 2023). "However, the downregulation of FTO at the protein level is found in intrahepatic cholangiocarcinoma (ICC), the second most common form of primary liver cancer." (PMID 32111216, 2020). "In patients with intrahepatic cholangiocarcinoma (ICC), the expression level of FTO is lower." (PMID 39295872, 2024). "For example, depletion of FTO induces suppression of LILRB4 in AML, and ALKBH5 facilitates expression of PD-L1 in intrahepatic cholangiocarcinoma (ICC)." (PMID 36810281, 2023).
liver cancer (16 papers, 2020 to 2025). An epithelial or non-epithelial malignant neoplasm that arises from the liver. "In addition, upregulation of FTO expression in patients with liver cancer is associated with high Edmondson grade, which is an independent prognostic factor for liver cancer." (PMID 38166832, 2024). "inhibiting liver cancer tumorigenesis and metastasis through the circGPR137B/miR-4739/FTO feedback loop." (PMID 40224186, 2025). "Together, these results indicate that both ALKBH5 and FTO regulate the expression of ATF4 in liver cancer cells treated with SOR." (PMID 39199320, 2024). "FTO promoted tumor progression in liver cancer, lung cancer, breast cancer, cervical cancer, and colorectal cancer." (PMID 35945641, 2022). "Since its identification as the demethylase of m6A, FTO has been reported to play an important role in many cancers including liver cancer 138-141." (PMID 33390849, 2021). "Some researchers have found that the overexpression of FTO is related to poor prognosis in patients with liver cancer." (PMID 34246319, 2021). "These conflicting functions of FTO in the two major types of primary liver cancer again raise the possibility of context-specific m6A landscapes and functions between HCC and ICC." (PMID 32111216, 2020). "In terms of the expression of FTO, its down-regulation significantly advance the content of m6A in total RNA, and the increased expression may restrain the growth and metastasis of liver cancer cells." (PMID 38166832, 2024). "However, in order to better understand the relationship between liver cancer development and FTO, further research is needed." (PMID 38166832, 2024). "FTO promotes the occurrence of liver cancer by mediating the demethylation of PKM2 mRNA." (PMID 35945641, 2022). "The expression and role of FTO in liver cancer is controversial." (PMID 34692544, 2021). "Despite the confirmed role of FTO in liver cancers, there is currently an absence of research on the m6A regulation mediated by FTO." (PMID 40316995, 2025). "The existing studies have not clarified the specific mechanism of FTO in the occurrence and development of liver cancer, and many research results point to the dual role of FTO in the occurrence and development of liver cancer." (PMID 38166832, 2024). "The m6A demethylase FTO and ALKBH5 play roles in promoting liver cancer progression." (PMID 35945641, 2022). "SIRT1 downregulates FTO expression through RANBP2-mediated SUMOylation and influences m6A RNA modification of tumour suppressors such as GNAO1 that mediate the development of liver cancer, thereby exerting oncogenic effects." (PMID 34246319, 2021). "The low-expression of demethylases (mainly FTO and ALKBH5) and concomitant m6A modifications in noncancerous peritumoral liver tissues are believed to enhance the malignant potential of liver cancer after resection." (PMID 34246319, 2021).
Sepsis (16 papers, 2020 to 2026). Sepsis is defined as life-threatening organ dysfunction caused by a dysregulated host response to infection. "FTO Ser95 site O-GlcNAcylation mutation aggravates S. Typhimurium or LPS-induced sepsis, while FTO O-GlcNAcylation suppresses the hyperinflammatory phenotype in mice." (PMID 40642069, 2025). "Curcumin-induced exosomal FTO from bone marrow stem cells alleviates sepsis-associated acute kidney injury by modulating the m6A methylation of OXSR1." (PMID 40989844, 2025). "FTO Ser95 site O-GlcNAcylation mutation aggravates S. Typhimurium or LPS-induced hyperinflammation and sepsis." (PMID 40642069, 2025). "Overall, NSUN7, NOP2, PUS1, PUS3, and FTO were identified as important diagnostic markers for sepsis." (PMID 37701433, 2023). "As shown, either deletion of Ythdf1 or forced expression of FTO in macrophages caused more mortality, boosted inflammatory response, and worse heart dysfunction in animal sepsis models." (PMID 36864027, 2023). "In sepsis‐induced cardiac injuries, FTO inhibited ferroptosis to relieve heart inflammation and dysfunction in mice by regulating BACH1 expression." (PMID 39739936, 2025). "Our findings reveal a previously unreported mechanism by which FTO O-GlcNAcylation acts as a negative regulator of inflammatory sepsis." (PMID 40642069, 2025). "In sepsis, the down-regulation of FTO leads to evidently increasing the total levels of m6A modification upon exposure to ferroptosis-inducing compounds." (PMID 36820206, 2023). "The genes TPSO, CYP1B1, LCN2, CLIC2, and ELL2 were up-regulated and FTO was down-regulated in sepsis compared to the uncomplicated infections (p < 0.05)." (PMID 36820206, 2023). "Barnesiellaceae was the main different gut microbiota between subjects with different genotype of FTO at baseline in our study, which plays a crucial role in maintaining health status, including prevent blood stream infection (BSI) and other diseases." (PMID 36185685, 2022). "The discovery of FTO and its downstream targets provides new insights into sepsis pathogenesis and may offer a foundation for developing novel therapeutic strategies." (PMID 41789088, 2026). "Taken together, our findings reveal that FTO O-GlcNAcylation promotes its ubiquitination degradation, and thus maintains the negative feedback control of macrophage inflammatory cytokine storm in sepsis." (PMID 40642069, 2025). "Recently, FTO has been highlighted for its role in promoting inflammation and sepsis." (PMID 40642069, 2025). "FTO is considered to be a biomarker for the clinic diagnose of sepsis." (PMID 39739936, 2025). "Based on our data, the combination of SIRT1 and FTO inhibitors which contribute to m6A methylation increases might be an effective therapeutic approach for the prevention or management of sepsis and COVID-19 in clinic." (PMID 36864027, 2023). "Finally, by using machine learning, we identified five hub RMGs (NSUN7, FTO, NOP2, PUS1, and PUS3), which showed efficient diagnostic value of sepsis." (PMID 37701433, 2023). "Firstly, we determined the genes expression in PBMCs by qRT-PCR analysis, and found the expression of NSUN7, NOP2, PUS1 and PUS3 in septic patients (septic shock and sepsis) at day 1 were significantly higher than in healthy volunteers, and FTO expression was lower in septic patients." (PMID 37701433, 2023). "In this predictive nomogram, the expression levels of FTO, HNRNPC, RBMX, YTHDC1, LRPPRC, and RBM15B were negatively associated with the risk score of patients with sepsis and were regarded as protective factors in sepsis." (PMID 36781867, 2023). "Taken together, our study also raises the possibility that FTO could be a potential target to attenuate cardiac inflammation and dysfunction during endotoxemia or sepsis." (PMID 34581943, 2022). "In addition, we identified that five RMGs (NSUN7, NOP2, PUS1, PUS3 and FTO) could function as biomarkers for clinic diagnose of sepsis." (PMID 37701433, 2023).
Sepsis (continued). "GO analysis of the DE RBPs in sepsis identified terms that were mostly enriched in the immune/inflammatory response; we identified significant differences in 8 down-regulated RBPs in sepsis, including DDX24, CBFA2T2, NOP, ILF3, DNMT1, FTO, PPRC1, NOLC1." (PMID 37749550, 2023). "We found greater enrichment of immune cells in sepsis patients with higher FTO and HNRNPC expression, which indicated that sepsis patients with higher FTO and HNRNPC expression had a more positive immune response to sepsis." (PMID 36781867, 2023). "Except for CYP4V2, there were also three genes down-regulated in sepsis, including ALOX15, BCL2, and FTO." (PMID 36820206, 2023). "To predict the occurrence of sepsis, we constructed a nomogram model for diagnosing sepsis based on the expression levels of five hub RMGs (NSUN7, FTO, NOP2, PUS1 and PUS3)." (PMID 37701433, 2023). "Third, FTO O-GlcNAcylation promotes TRIM21-mediated FTO ubiquitination degradation, which induces Socs1 m6A methylation and sustains SOCS1 induction to maintain the negative feedback control of macrophage inflammatory cytokine storm in sepsis." (PMID 40642069, 2025). "We observed substantial heterogeneity in the expression of demethylases (ALKBH5, FTO) and methyltransferase complex components (WTAP, METTL3, METTL14), suggesting their potential involvement in the epigenetic regulation of immune function during sepsis." (PMID 40625751, 2025). "Additionally, when compared to sepsis shock, we found TPSO, GCLM, CYP1B1, LCN2, and LTF were up-regulated and the FTO and CYP4V2 were down-regulated in the sepsis (p < 0.05)." (PMID 36820206, 2023). "We observed that enhancing O-GlcNAcylation of FTO using an OGA inhibitor (TMG) decreased LPS-induced TNF-α/IL-1β/IL-6 inflammation and reduced septic mouse mortality, which may constitute a protective mechanism to limit exacerbated inflammation in acute stress conditions such as LPS-induced sepsis." (PMID 40642069, 2025). "Thus, the expression levels of the eight RBPs (DDX24, CBFA2T2, NOP14, ILF3, DNMT1, FTO, PPRC1, and NOLC1) were altered in the patients with sepsis might potentially be useful as novel biomarkers as well as targets to facilitate the diagnosis and management of sepsis." (PMID 37749550, 2023). "Using qRT-PCR, we detected that the expression of METTL3 and WTAP in the aorta was significantly downregulated during sepsis, while that of YTHDF 1, YTHDF 3, METTL14, and FTO did not change significantly." (PMID 34507301, 2021).
esophageal squamous cell carcinoma (15 papers, 2021 to 2025). Esophageal squamous cell carcinoma (ESCC) is a type of esophageal carcinoma (EC) that can affect any part of the esophagus, but is usually located in the upper or middle third. "In esophageal squamous cell carcinoma (ESCC), FTO is highly expressed and associated with the demethylation of LINC00022, thereby promoting tumor growth in vivo." (PMID 39192357, 2024). "Research demonstrated that increased FTO in esophageal squamous cell carcinoma (ESCC) lowered the m6A methylation of LINC00022 transcripts, causing LINC000222 degradation to be repressed by YTHDF2." (PMID 38125749, 2023). "The upregulation of DLEU2 promoted tumorigenesis of esophageal squamous cell carcinoma, which was epigenetically mediated by m6A demethylase FTO." (PMID 35789547, 2023). "Further exploring data indicated that LncRNA CASC15 promoted esophageal squamous cell carcinoma carcinogenesis by decreasing single minded 2 (SIM2) stability via FTO-regulated demethylation." (PMID 37365581, 2023). "Besides, the long noncoding RNA CASC15 has been observed to interact with FTO to regulate the progression of esophageal squamous cell carcinoma." (PMID 38508309, 2024). "Conversely, in esophageal squamous cell carcinoma (ESCC), overexpression of FTO promotes LINC00022-dependent cell proliferation and tumor growth." (PMID 40271153, 2025). "In esophageal squamous cell carcinoma (ESCC), the m6A demethylase FTO stabilizes the long non-coding RNA LINK-A, promoting cell proliferation and chemoresistance." (PMID 40271153, 2025). "By using the in vitro MeRIP-seq and RNA-seq assays, we discovered that the mRNA demethylase FTO was significantly up-regulated in esophageal squamous cell carcinoma (ESCC) tissues and cells." (PMID 35524932, 2022). "FTO demethylates the LncRNA LINC00022 at the m6A position, promoting the formation of tumours in ESCC (esophageal squamous cell carcinoma) in vivo." (PMID 39039912, 2024). "In esophageal squamous cell carcinoma, up-regulation of LINC00022 mediated by FTO promotes cell proliferation and tumor growth." (PMID 36309694, 2022). "In esophageal squamous cell carcinoma, ERBB2 was identified as the target of FTO using m6A-seq and RNA-seq assays, and YTHDF1 then binds and stabilizes ERBB2 mRNA." (PMID 36360294, 2022). "For examples, FTO can decrease m6A methylation of LINC00022 transcript, contributing to the suppression of LINC00022 decay via the m6A reader YTHDF2 in esophageal squamous cell carcinoma (ESCC), thereby promoting the cell proliferation and tumor growth of ESCC." (PMID 34787056, 2022). "As for m6A erasers, FTO is reported to demethylate m6A on LINC00022, a lipogenesis-related lncRNA, leading to the upregulation of LINC00022 in esophageal squamous cell carcinoma (ESCC) cells." (PMID 36553003, 2022).
Parkinson disease (15 papers, 2017 to 2025). A progressive degenerative disorder of the central nervous system characterized by loss of dopamine producing neurons in the substantia nigra and the presence of Lewy bodies in the substantia nigra and locus coeruleus. "Aberrant expressions of METTL3 and FTO have been associated with Alzheimer’s or Parkinson’s disease." (PMID 37990254, 2023). "Furthermore, FTO, and indeed m6A, may also be associated with Parkinson’s disease (PD), as dopaminergic signaling is negatively affected upon the inactivation of FTO." (PMID 33402207, 2021). "The survival of dopaminergic neurons in Parkinson’s disease (PD) is critically dependent on m6A levels, which are regulated by FTO through its role in regulating midbrain dopamine signaling and maintaining the normal function of dopamine D2-like receptors." (PMID 41446042, 2025). "Recent studies showed that entacapone, a catechol‐o‐methyl transferase (COMT) inhibitor currently applied for Parkinson's disease, can inhibit FTO enzyme." (PMID 36534072, 2023). "Additionally, entacapone, a catechol-O-methyltransferase inhibitor used in Parkinson’s disease, was also identified as an FTO inhibitor, influencing metabolic homeostasis by selectively inhibiting FTO activity." (PMID 40428320, 2025). "Therefore, the results of this study illustrate the important role of FTO in Parkinson’s disease (PD) through the ferroptosis." (PMID 38550378, 2024). "FTO overexpression upregulated the level of ephin-B2 through an m6A-YTHDF2-dependent manner and reversed the downregulation of ephin-B2 in the manganese-induced parkinsonism model." (PMID 37762200, 2023).
atherosclerosis (14 papers, 2021 to 2026). A disease characterized by the build-up of fatty material and calcium deposition in the arterial wall resulting in partial or complete occlusion of the arterial lumen. "Secondly, our findings reveal that FTO-mediated m6A RNA demethylation is in part implicated in the pharmacological effects of Rb1 against NETs-induced endothelial activation in atherosclerosis." (PMID 40771928, 2025). "FTO plays a crucial role in regulating atherosclerosis by directly mediating the expression of CD40 ligand (CD40L)." (PMID 39787159, 2025). "FTO affects macrophage foam cell transformation, a critical step in the initiation and progression of atherosclerosis, primarily by activating AMPK-induced cholesterol flux and inhibiting PPAR-γ-mediated lipid uptake." (PMID 41367876, 2025). "FTO is also found to inhibit macrophage lipid influx and accelerate cholesterol efflux, which delays foam cell formation and atherosclerosis development." (PMID 36894991, 2023). "Another study has demonstrated that the expression of FTO was significantly decreased in the human carotid artery plaques of early atherosclerosis." (PMID 38097926, 2023). "Several FTO polymorphisms are associated with increased risk for weight gain and the APOE ε4 variant is a genetic risk factor for atherosclerosis and CVD in humans." (PMID 35454109, 2022). "In this study, we revealed that RORB, RORC, PER1, CRY1, FTO were in close relationship with atherosclerosis, particularly in atherosclerotic lesions with higher immune infiltration." (PMID 34082770, 2021). "In addition, inhibition of FTO is closely related to anti-atherosclerosis by regulating the PCD pathway." (PMID 39227813, 2024). "Accordingly, inhibition of FTO is expected to be used in the treatment of atherosclerosis." (PMID 39227813, 2024). "All the available evidence suggests that chronopharmacology-based therapy targeting RORB, RORC, PER1, CRY1, or FTO might constitute another approach for the treatment of atherosclerosis." (PMID 34082770, 2021). "Furthermore, we also investigated FTO-mediated m6A RNA demethylation to understand the mechanisms contributing to the pharmacological effects of Rb1 against NETs-induced endothelial activation in atherosclerosis." (PMID 40771928, 2025). "At least, these data revealed that in atherosclerosis and other CVDs, m6A writer METTL14 is upregulated and eraser FTO is downregulated." (PMID 35211628, 2022). "While it’s been reported that the demethylase FTO (alpha-ketoglutarate-dependent dioxygenase) coimmunoprecipitates with CRY1/2, studies also showed that upregulation of FTO and CRY1 attenuated atherosclerosis through macrophages and proinflammatory factors respectively." (PMID 34082770, 2021). "In atherosclerosis, a chronic inflammatory disease of arteries, FTO expression was not altered, but increased m6A modification also influenced the development of atherosclerosis." (PMID 34881240, 2021). "A putative mechanistic link between APOE and FTO is underscored by studies showing that overexpression of FTO in APOE-deficient mice reduces cholesterol and inflammatory cytokine synthesis by macrophages and alleviates atherosclerosis associated with the absence of APOE." (PMID 35454109, 2022).